PIK3CA (phosphatidylinositol-4,5-bisphosphate 3-kinase catalytic subunit alpha)
Diseases named in the same sentence as PIK3CA in open-access papers (continued):
Sharing a sentence is not in itself a finding about the gene and the disease.
tumor (continued). "Progression of prostate cancer and multi-drug-resistant tumour was significantly associated with PI3kinase pathway hyperactivation, either due to PTEN modulation or due to hyperactivation of PIK3CA, AKT, mTOR or any other proteins of the pathway." (PMID 38774756, 2024). "The efficacy of alpelisib in reducing tumor volume was slightly improved (not statistically significant) when alpelisib was combined with metformin and dapagliflozin in ER+/PIK3CA mutant HBRX3077 PDX tumor-bearing nude rats." (PMID 39177931, 2024). "A prespecified exploratory analysis of this study examined the role of different biomarkers at baseline, including TILs, PD-L1, CD8, HER2 expression and amplification, tumor mutational burden (TMB), effector T-cell gene signature, and PIK3CA mutational status." (PMID 39062065, 2024). "Significant differences in the prevalence of potentially targetable genomic alterations (ATM, BRAF, BRCA2, ERBB2, IDH1, PIK3CA, and PTEN) were observed in MTAP-loss tumors and varied according to tumor type." (PMID 38330461, 2024). "The tumor tissue was also positive for well-characterized activating alterations in FGFR1 p.Asn546Lys and two variants in PIK3CA p.His1047Arg and p.His1047Tyr." (PMID 39309743, 2024). "Amplification of the PIK3CA gene was observed in 5 HR+/HER2- tumours (3.5%) and one TNBC patient (2%)." (PMID 39322687, 2024). "Using our quantitative iMALDI-MS assay, we observed significant inter-tumor variability in the amount of AKT1 and AKT2 protein, with as much as a 4-fold difference among PIK3CA-mutated tumors." (PMID 38954770, 2024). "The results also identify the potential correlation between PTEN, PIK3CA gene expression, and parameters such as tumor grade and neuroinvasion." (PMID 38891994, 2024). "The only association we observed in our study between PIK3CA mutation status and the levels of studied proteins was the decreased ADAMTS10 protein concentration in the PIK3CA-mutated tumor group." (PMID 39329961, 2024). "Among the five identified ICDGs, NT5E, HSP90AA1, and EIF2AK3 exhibited heightened expression levels in tumor tissues, while PIK3CA and P2RX7 demonstrated elevated expression levels in normal tissues." (PMID 38575204, 2024). "The five-gene signature’s expression was validated utilizing the TCGA database, with NT5E, HSP90AA1, and EIF2AK3 demonstrating elevated expression levels in tumor tissues, while PIK3CA and P2RX7 exhibited heightened expression in normal tissues." (PMID 38575204, 2024). "In this study, PIK3CA and BRAF mutations were less frequent in the rectum than in the other primary tumor locations (right and left sides)." (PMID 38409377, 2024). "Another significant aspect for the identified PIK3CA mutant neoantigen and the corresponding TCRs resides within the applicable platform of tumor vaccine." (PMID 38832948, 2024).
tumor (continued). "This study aimed to investigate the prognostic value of c-MET-positive circulating tumor cells (cMET+ CTCs), ESR1/PIK3CA mutations, and cell-free DNA (cfDNA) concentrations in patients with hormone receptor-positive (HR+) metastatic breast cancer (mBC)." (PMID 38238761, 2024). "PIK3CA alterations were found in 43.5% of HR+/HER2- tumours (n = 47), 50% of HER2-enriched lesions (n = 2), 33.3% of HR+/HER2+ (n = 3) and 11.1% of TNBCs (n = 5)." (PMID 39322687, 2024). "Elucidating PIK3CA's multifaceted influence on the tumor microenvironment and its role in tumor tropism has paved the way for targeted therapeutic strategies aimed at disrupting these pathways." (PMID 39369580, 2024). "For patients with paired tissue‐plasma studies (n = 64), PIK3CA determination was performed in primary tumor tissue for 60.9% and in metastases for 39.1%." (PMID 39235099, 2024). "This intricate signaling cascade, tightly regulated by PIK3CA, ultimately influences various cellular processes, including those that govern a tumor cell's propensity for migration and invasion – hallmarks of tumor tropism." (PMID 39369580, 2024). "A PIK3CA p.E542K mutation was identified in CRC-1 with an allele frequency of 57.5%, suggesting possible founding mutation during early tumor formation stages." (PMID 38310289, 2024). "As with the xenograft models, the combination of CB-839 and 5-FU decreased the levels of 14-3-3ε in the syngeneic CMT93 and MC38 Pik3ca E545K mutant tumor models." (PMID 38194275, 2024). "PIK3CA gene mutation and its resulting protein dysfunction can trigger dysregulation of PI3K/Akt signaling pathway, thereby promoting tumor formation and development." (PMID 38957396, 2024). "Despite that, in the present study, among four samples presenting GATA3 alterations, one luminal A tumor also presented an activated PIK3CA." (PMID 39208653, 2024). "Several tumors harboring genomic alterations with US Food and Drug Administration-approved indications in other tumor types were found including NF1, PIK3CA, EGFR Exon 19/20 insertions, and BRAF V600E mutations." (PMID 39191445, 2024). "This review meticulously highlights the association between PIK3CA mutations and distinct TNBC subtypes, elucidating the gene's multifaceted contributions to tumor tropism." (PMID 39369580, 2024). "The approval is restricted to patients whose tumours harbour oncogenic alterations of the PIK3CA, AKT, or PTEN gene." (PMID 39322687, 2024).
tumor (continued). "L-NMMA+alpelisib therapy resulted in a significant inhibition of tumor growth relative to single-agent alpelisib therapy in PIK3CA-mutant MpBC PDX models (BCM-3807 [p = 0.0456], PIM-010 [p = 0.0079], and PIM-084 [p = 0.016])." (PMID 39737957, 2024). "The next-generation sequencing has shown PIK3CA E545K, SMAD4 1309-1G, and ALK E717K gene mutations, receptor tyrosine kinase 2 (ErbB-2) amplification, microsatellite stability, and low tumor mutational burden of 6.3 mutations per megabase." (PMID 38215117, 2024). "A high rate of PIK3CA mutation (31 out of 67, or 46.3%) was discovered in CRC patients, suggesting possible tumor progression mechanisms and targeted therapy opportunities." (PMID 38310289, 2024). "For example, PIK3CA gene mutation can activate the PI3K/AKT signaling pathway, increase the mutational load and generation of neoantigens in tumor cells, thereby increasing the response rate of vaccines or cell therapy." (PMID 39555098, 2024). "Clinically, elevated expression of PIK3CA has been shown to be correlated with tumour invasion and poor prognosis among cancer patients." (PMID 38336976, 2024). "Mutations in the PIK3CA gene have been associated with several clinical and pathological features in CRC, such as age of onset, tumor location, histological grading, and microsatellite instability status." (PMID 39555098, 2024). "Recently, the identification of mutations in PIK3CA and AKT1 genes, or loss of PTEN, detected in both tissue and circulating tumor DNA, has emerged as a resistance mechanism for disease progression after first-line therapy." (PMID 39448637, 2024). "PIK3CA mutations, AKT alterations, and the loss of the PTEN tumor suppressor can lead to the constitutive activation of the PI3K/AKT signaling pathway." (PMID 39769140, 2024). "These alterations of the PIK3CA gene correlated mainly with decreased disease-free survival and increased tumor size." (PMID 39062539, 2024). "Within the same sample, multiple pathogenic alterations of the PIK3CA gene were found in one TNBC (2%) and 10 HR+/HER2- tumours (9%)." (PMID 39322687, 2024). "Specifically, seven cases of GC with mutated PIK3CA and unstable MSI were located in the lower-third of the tumor." (PMID 38392195, 2024). "The PI3K/AKT/PTEN pathway was the most altered with one or more of the pathway member genes PIK3/AKT/PTEN affected in 62% (98/158) patients and 43% of tumours harbouring a PIK3CA alteration." (PMID 38812774, 2024).
tumor (continued). "There is one possible reason that alterations in different exons of PIK3CA have varying impacts on tumor development and progression and differ in prognostic value." (PMID 37715134, 2023). "In search of actionable tumor mutations, whole-genome sequencing (WGS) was performed, which identified an activating mutation in the PIK3CA gene." (PMID 37086483, 2023). "The ESMO rated PIK3CA mutation analysis with ESCAT scale IA and in Germany, the recommendation for PIK3CA mutation profiling in primary tumor tissue, metastasis or plasma was confirmed in 2023." (PMID 38001722, 2023). "In this study, the combination of low-dose metronomic VRL and alpelisib revealed a significant reduction of cell viability and proliferation with synergistic anti-tumor effects in HR-positive, HER2-negative, PIK3CA-mutated BC cell lines." (PMID 36998707, 2023). "The emergence of some driver gene mutations during treatments was detected by circulating tumor DNA analysis, revealing mutations in RB1 and to a larger extent in PIK3CA and the ERα gene ESR1 itself." (PMID 36869202, 2023). "Classically, whole-exome association studies in HPVOPC have concluded that SNVs in specific genes, such as within the PIK3CA pathway, largely account for the malignant tumor phenotype." (PMID 37686653, 2023). "Alpelisib also showed synergistic anti-tumor activity with paclitaxel in gastric cancer with higher effects in PIK3CA-mutant cells." (PMID 36765741, 2023). "FDA’s approval of alpelisib and fulvestrant in PIK3CA-mutated HR + /HER2− ABC, along with the updated ASCO guidelines, recognized PIK3CA mutation (tumor or liquid biopsy) as a biomarker to guide systemic therapy in ABC62,63." (PMID 37684290, 2023). "This subset of PIK3CA mutations observed in HPV-positive HNC plays a pivotal role in tumorigenesis, potentially contributing to increased cell proliferation, tumor growth, and survival." (PMID 38275384, 2023). "ARID1A and PIK3CA mutations are frequently found together in OCCC, and they are synergistic in tumour formation." (PMID 38275587, 2023). "For instance, dMMR/MSI-H CRC patients with low TMB, immunosuppressive tumor microenvironment, or mutation in the PTEN gene or PIK3CA gene are resistant to ICIs, while pMMR/MSS CRC patients with a mutation in POLE or POLD1 gene are sensitive to ICIs." (PMID 37441082, 2023). "The “MX-99” tumour also harboured somatic mutation in PIK3R1 (NM_181504: p.Y2fs), which is a regulatory subunit for PIK3CA with tumour-suppressor properties." (PMID 36522480, 2023). "For patients with metastatic ILC, mutations in CDH1, NF1, PIK3CA, and TBX3, measured as tumor mutational burden (TMB), are higher than for patients with metastatic IDC." (PMID 37428725, 2023). "Genomic amplification of both PIK3CA and AKT genes has been linked to early stages of tumor formation." (PMID 37109059, 2023). "A third patient had detectable PIK3CA and ESR1 mutations at baseline that became undetectable in all subsequent visits during the 36 months of treatment, and sustained tumor-size reduction was observed throughout treatment." (PMID 37580773, 2023). "The results showed tumor-specific mutations such as missense mutation in exon 9 of PIK3CA P. e542k and germline genes mutations of PRF1, SBDS, and a tumor mutation burden of 12.89 mutations/Mb." (PMID 36930086, 2023). "In particular, a high frequency of PIK3CA and PTEN gene mutations in HPV-positive HNCs have been reported, with a significant association between PIK3CA, PTEN, and tumor HPV status." (PMID 37237486, 2023).
tumor (continued). "In the present study, we investigated the prognostic value of the mutational status of the KRAS, NRAS, PIK3CA and BRAF genes detected in tumor biopsies and plasma samples from 51 synchronous metastatic colorectal cancer (SMCC) patients." (PMID 37176143, 2023). "This included ST3932 tumours which in addition to being PTEN null, PIK3CA mutant also carried a RB1 mutation." (PMID 37543694, 2023). "MEN1611 monotherapy showed antitumor activity in several HER2-positive trastuzumab-resistant PIK3CA-mutant PDXs harboring different concomitant genomic aberrations, subsequently inducing tumor-stasis or tumor regression." (PMID 36913051, 2023). "We found that let‐7c‐3p regulates the PI3K/AKT/mTOR signaling pathway by inhibiting the expression of PIK3CA, exerting an anti‐tumor effect." (PMID 36412203, 2023). "One was that the PIK3CA or KRAS mutation was detected in CTCs, even when the corresponding primary tumor was judged to be a wild type (Pt." (PMID 36672711, 2023). "In this case, PIK3CA overexpression was restricted to the head and neck, and tumours were generated in 100% of mice after 10–12 months." (PMID 36765175, 2023). "HER2 status (per central assessment), hormone receptor status, PIK3CA mutation status, HER2/HER3 mRNA levels, tumor-infiltrating lymphocyte levels, PD-L1 status, and NanoString data were analyzed." (PMID 36631725, 2023). "To confirm no substantial off-targeting in our vector system, we performed WGS of one Pik3ca-edited tumor and, for comparison, one mouse normal ear punch." (PMID 37172086, 2023). "In order to maximise combination therapies, high-throughput molecular profiling approaches will be essential to promote an accurate matching of patients with PIK3CA aberrations to specific tumor subtypes." (PMID 36765661, 2023). "CTG-1260 tumors harbor both an ESR1D538G mutation and mutations in PIK3CA and PTEN, and were resistant to fulvestrant in vivo and both single and combination RMC-6272 treatment significantly reduced tumor growth." (PMID 37264081, 2023). "Of the 169 participants with tumours classified as ctDNA PIK3CA NMD, 68 (40.2%) and 101 (59.8%) were treated with PBO + FUL and TAS + FUL, respectively." (PMID 36892268, 2023). "In PIK3CA/AKT1/PTEN-altered tumours, this regimen was significantly beneficial, with a median PFS of 9.3 months." (PMID 37489050, 2023). "Another potential target for the treatment of this tumor is the PIK3CA/AKT pathway, which is dysregulated in approximately 25–30% of TNBC patients." (PMID 37298642, 2023).